IGF2BP1 (insulin like growth factor 2 mRNA binding protein 1)
Diseases named in the same sentence as IGF2BP1 in open-access papers (continued):
Sharing a sentence is not in itself a finding about the gene and the disease.
pancreatic cancer (11 papers, 2012 to 2026). "In detail, IGF2BP1 has been identified as a key player in pancreatic cancer and was found to be significantly upregulated in this malignancy." (PMID 40427100, 2025). "The overexpression of IGF2BP1 was correlated with tumour size and shorter overall survival (OS) in pancreatic cancer patients, highlighting its clinical relevance as a prognostic marker." (PMID 40427100, 2025). "IGF2BP1 was discovered to influence pancreatic cancer carcinogenesis by modifying the Akt signaling pathway, IGF2B2 by directly binding to and stabilizing GLUT1 mRNA, and IGF2B3 through regulating mRNA-miRNA interaction." (PMID 35355828, 2022). "In the LinkedOmics dataset, the high expression of IGF2BP1, IGF2BP2, and IGF2BP3 was significantly associated with the poor overall survival of pancreatic cancer patients." (PMID 33246429, 2020). "Since the MYC mRNA is known to be bound and stabilized by IGF2BP1 in a m6A-dependent manner, the authors speculated that gemcitabine might interfere with the WTAP/MYC/IGF2BP1 axis to inhibit pancreatic cancer progression." (PMID 40427100, 2025). "Moreover, IGF2BP1 was shown to contribute to gemcitabine resistance of pancreatic cancer cells via multiple mechanisms." (PMID 40427100, 2025). "Furthermore, pancreatic cancer patients with lower METTL3, METTL14, RBMX, FTO, ALKBH5, YTHDF1, and YTHDC1 mRNA expression levels or higher VIRMA, HNRNPA2B1, EIF3A, IGF2BP1, IGF2BP2, and IGF2BP3 mRNA expression levels had significantly poorer OS (P < 0.05)." (PMID 34330301, 2021). "According to ONCOMINE, the expression of IGF2BP1 in pancreatic cancer tissue was not significantly different from that in normal pancreatic tissue." (PMID 33246429, 2020). "Furthermore, we performed a prognostic analysis of IGF2BP1, IGF2BP2, and IGF2BP3 in pancreatic cancer with the LinkedOmics and GEPIA datasets." (PMID 33246429, 2020). "The results showed that the expression of the IGF2BP1 gene in pancreatic cancer tissue was not different from that in normal pancreatic tissue." (PMID 33246429, 2020). "Using pancreatic cancer cell lines, we found that IGF2BP1 could not regulate the mRNA expression of c-myc but was positively related to the protein level of c-myc." (PMID 33122827, 2021). "The IGF2BP1 mRNA expression level was not upregulated in pancreatic cancer, but the IGF2BP2 and IGF2BP3 mRNA expression levels were upregulated in pancreatic cancer to varying degrees." (PMID 33246429, 2020).
clear cell renal cell carcinoma (6 papers, 2022 to 2023). "The landscape analysis based on TCGA shows that IGF2BP1 level is increased in clear cell renal cell carcinoma (ccRCC) and high expression of IGF2BP1 is closely correlated with the lower survival of ccRCC patients." (PMID 37055798, 2023). "IGF2BP1 participates in clear cell renal cell carcinoma (ccRCC) by recognizing sites on LDHA mRNA modified with m6A marks, increasing LDHA mRNA stability and accelerating aerobic glycolysis." (PMID 37055798, 2023). "We identified five survival-related genes (AGR2, HAO2, IGF2BP1, MCCD1 and OLFM4) in clear cell renal carcinoma patients." (PMID 36516496, 2022). "The highly expressed IGF2BP1 directly binds to the m6A modification site on LDHA mRNA, thereby enhancing the stability of LDHA mRNA and promoting glycolysis and malignant phenotype of clear cell renal cell carcinoma." (PMID 37582735, 2023).
non-small cell lung carcinoma (6 papers, 2020 to 2024). A group of at least three distinct histological types of lung cancer, including non-small cell squamous cell carcinoma, adenocarcinoma, and large cell carcinoma. "The similar trend was also identified in non-small cell lung cancer, and high expression level of IGF2BP1 facilitates the disease progression." (PMID 33796449, 2021). "Previously, this microRNA was found to suppress cell proliferation and invasion in non-small cell lung cancer by inhibiting IGF2BP1." (PMID 32545414, 2020). "In addition, a small molecule inhibitor of IGF2BP1 suppressed cell migration and colony formation in soft agar in non-small-cell lung carcinoma H1299 cells." (PMID 35794212, 2022).
Obesity (6 papers, 2016 to 2025). Accumulation of substantial excess body fat. "Several of the identified loci have been implicated in ASCVD risk factors such as circulating lipids (LPA-PLG, APOE, TRIB1, KANK2), diabetes (CDKN2B-AS1, IGF2BP1) and obesity (LEPR, IGF2BP1)." (PMID 40164586, 2025). "For example, of the four loci discovered by the recently discussed GWAS in BF% (in or near COBLL1/GRB14, IGF2BP1, PLA2G6, CRTC1) and in the most recent GWAS of obesity as measured by BMI only a very small number of these overall obesity loci exhibited sexual dimorphism (approximately 3–5%)." (PMID 28073971, 2017).
prostate carcinoma (6 papers, 2020 to 2025). A carcinoma that arises from epithelial cells of the prostate gland. "Consistently, another analysis using TCGA data indicated that the expression of IGF2BP1 was negatively associated with survival in prostate cancer." (PMID 32950970, 2020).
seminoma (6 papers, 2020 to 2025). A radiosensitive malignant germ cell tumor found in the testis (especially undescended), and extragonadal sites (anterior mediastinum and pineal gland). "TFAP2c, the transcription factor AP-2 family member, was methylated by METTL3 and recognized by IGF2BP1, which enhances the mRNA stability of TFAP2c, thereby making seminoma resistant to cisplatin." (PMID 40180937, 2025). "In our assays in the present study, the biological effect of METTL3 overexpression on seminoma cells was attenuated or reversed by inhibition of IGF2BP1, suggesting a close relation and synergism of the ‘writer’ and ‘reader’ in m6A modification." (PMID 32857912, 2020). "In oral squamous cell carcinoma and seminoma cells, m6A/IGF2BP1-mediated mRNA stabilization of estrogen-related receptor alpha (ERRα) and transcription factor-activating enhancer-binding protein 2C (TFAP2C) can facilitate tumor cell survival upon cisplatin treatment." (PMID 40584294, 2025). "For example, methyltransferase‐like 3 (METTL3) could stabilise the transcription factor AP‐2 gamma (TFAP2C) mRNA in an insulin‐like growth factor 2 mRNA binding protein 1 (IGF2BP1)‐dependent mode and further enhance cisplatin resistance in seminoma." (PMID 35696608, 2022). "Collectively, we showed the interactions of the METTL3/IGF2BP1/TFAP2C signalling pathway and unveiled its contributions to in vivo CDDP resistance in seminoma." (PMID 32857912, 2020). "Two molecules, methyltransferase‐like protein 3 (METTL3) and insulin‐like growth factor 2 mRNA‐binding protein 1 (IGF2BP1), were found to play crucial roles in potentiating resistance to CDDP through m6A methylation of transcription factor‐activating enhancer‐binding protein 2C (TFAP2C) in seminoma." (PMID 32857912, 2020).
nasopharyngeal carcinoma (5 papers, 2020 to 2025). A carcinoma arising from the nasopharyngeal epithelium. "For example, in the treatment of human nasopharyngeal carcinoma (NPC), when a conserved but oncogenic LncRNA THOR (testis-associated oncogenic LncRNA, ENSG00000226856) was downregulated, the function of IGF2BP1 was simultaneously inhibited." (PMID 36226062, 2022). "METTL3/m6A/IGF2BP1 axis suppresses autophagy and enhances stemness by enhancing the stabilization and up-regulation of LINC00313 in nasopharyngeal carcinoma cells." (PMID 40584294, 2025). "Similarly, knockdown of lnc-HTOR or IGF2BP1 by CRISPR/Cas9 gene-editing methods mimicked the effects and abolished the requirement for Triptonide in nasopharyngeal carcinoma cells." (PMID 32850817, 2020).
renal cell carcinoma (5 papers, 2017 to 2022). "In addition, the overexpression of THOR also results in the upregulation of IGF2BP1 to enhance the survival and proliferation of human renal cell carcinoma (RCC) cells." (PMID 35534472, 2022). "In addition, AGR2 and IGF2BP1 promoted tumorigenesis by accelerating hypoxia state in renal cell carcinoma cell line." (PMID 36516496, 2022).
rhabdomyosarcoma (5 papers, 2018 to 2023). A rare aggressive malignant mesenchymal neoplasm arising from skeletal muscle. "In rhabdomyosarcomas, IGF2BP1 directly binds to cIAP1 mRNA and mediates its translation, regulating rhabdomyosarcoma cell death and drug resistance." (PMID 35945641, 2022). "IGF2BP1 is a critical modulator of cellular inhibitor of apoptosis 1 (cIAP1) expression and of apoptotic resistance in rhabdomyosarcoma (RMS), controlling cell death and drug resistance by medicating translation of cIAP1." (PMID 29954406, 2018). "Along these lines, it appears reasonable that IGF2BP1 supports MYC/N-driven proliferation capacity in embryonal neuroblasts, other childhood/youth cancers with strong MYC/N-dependency and aberration at Chr 17q, e.g. rhabdomyosarcoma and medulloblastoma, as well as carcinomas in general." (PMID 37246217, 2023).
atherosclerosis (4 papers, 2021 to 2025). A disease characterized by the build-up of fatty material and calcium deposition in the arterial wall resulting in partial or complete occlusion of the arterial lumen. "IGF2BP1 has been linked to coronary artery disease (CAD) and T2DM, and it has been proposed as a potential therapeutic target in atherosclerosis and diabetic angiopathy." (PMID 38008859, 2024).
esophageal squamous cell carcinoma (4 papers, 2023 to 2026). Esophageal squamous cell carcinoma (ESCC) is a type of esophageal carcinoma (EC) that can affect any part of the esophagus, but is usually located in the upper or middle third. "In esophageal squamous cell carcinoma (ESCC), WTAP mediates m6A modification on the lncRNA PDIA3P1, which is then recognized by IGF2BP1 to enhance its stability." (PMID 41522342, 2026).
lymph node metastasis (4 papers, 2022 to 2024). "High expression of insulin growth factor 2 mRNA binding protein 1 (IGF2BP1) is associated with a poor prognosis such as advanced clinical stage, increased tumor size, lymph node metastasis, and low survival rate of patients with HNSCC." (PMID 35449571, 2022). "Increased expression of IGF2BP1 correlated significantly with the tumor size, lymph node metastasis, distant metastasis, and clinical stage grade." (PMID 37340443, 2023). "Furthermore, increased IGF2BP1 expression was significantly correlated with clinical stage and lymph node metastasis." (PMID 38084791, 2024).
acute lymphoblastic leukemia (3 papers, 2017 to 2020). Leukemia with an acute onset, characterized by the presence of lymphoblasts in the bone marrow and the peripheral blood. "IGF2BP1 acts as oncogene in many types of solid tumors, and it has been identified as a novel IgH translocation partner in B acute lymphoblastic leukemia (ALL)." (PMID 28693523, 2017). "Cell lines with high expression of IGF2BP1 are AML-, chronic myeloid leukemia (CML)- and common acute lymphoblastic leukemia (cALL) cell lines." (PMID 32408494, 2020). "The role of IGF2BP1 in hematological malignancies, including acute myeloid leukemia (AML) and B acute lymphoblastic leukemia (ALL) was found, although its expression and exact function is little known." (PMID 29954406, 2018).
acute myeloid leukemia (3 papers, 2018 to 2022). Acute myeloid leukemia (AML) is a group of neoplasms arising from precursor cells committed to the myeloid cell-line differentiation. "In acute myeloid leukemia (AML), abnormal expression of m6A regulatory factors, including METL3, METTL14, FTO, ALKBH5, and IGF2BP1/2/3, can regulate the expression of MYC." (PMID 33926508, 2021).
anaplastic thyroid carcinoma (3 papers, 2013 to 2021). "Notably in this respect, the conserved upregulation or de novo synthesis of IGF2BP1 in cancer is primarily observed in progressed, de-differentiated malignancies, as demonstrated for instance in anaplastic thyroid carcinoma." (PMID 34026620, 2021).
B-cell acute lymphoblastic leukemia (3 papers, 2021 to 2025). A neoplasm of lymphoblasts committed to the B-cell lineage, typically composed of small to medium-sized blast cells. "Sharma et al54 validated the synergistic effect of IGF2BP1 (insulin-like growth factor 2 mRNA binding protein 1) with ETV6-RUNX1 and revealed the role of IGF2BP1 through mRNA stabilization in the oncogenic process of B-cell acute lymphoblastic leukemia." (PMID 40584293, 2025).
diabetes (3 papers, 2005 to 2025). "IGF2BP1 can interact and process the IGF2 transcripts, and its dysfunction was associated with tumorigenesis, drug resistance, and diabetes as well as insulin control." (PMID 34203267, 2021). "Moreover, several other genes between PECAM-1 and Igf2Bp1, such as Growth Hormone, STAT3, and STAT5 are involved in diabetic nephropathy or diabetes and an identified IDD4 interval spans STAT3." (PMID 16371158, 2005).
dwarfism (3 papers, 2019 to 2022). "IGF2BP1 is also associated with tumors, cancer, dwarfism, and other diseases, but its mechanism of fat regulation requires further study." (PMID 36552358, 2022). "These functions are essential for normal growth and development, as mice deficient in Igf2bp1 have dwarfism and impaired intestinal development." (PMID 32154328, 2020). "Insulin-like growth factor-2 mRNA-binding protein-1-deficient mice show dwarfism, impaired gut development, and downregulated IGF2 expression level at the embryonic stage." (PMID 31658691, 2019).
esophageal cancer (3 papers, 2021 to 2025). A primary or metastatic malignant neoplasm involving the esophagus. "Studies have shown that miR-454-3p overexpression can inhibit the expression of insulin-like growth factor 2 mRNA-binding protein 1 (IGF2BP1) at the protein and mRNA expression levels and thus inhibit the occurrence and development of esophageal cancer." (PMID 34234806, 2021). "Consistent with our study, IGF2BP1 is a poor prognostic factor for esophageal cancer." (PMID 34234806, 2021).
Ewing sarcoma (3 papers, 2019 to 2025). A small round cell tumor that lacks morphologic, immunohistochemical, and electron microscopic evidence of neuroectodermal differentiation. "While genes such as BCL11B and VRK1 are well characterized, others, such as IGF2BP1 and LSM6, remain poorly studied, yet they may offer valuable insights into the biology and vulnerabilities of Ewing sarcoma." (PMID 41444391, 2025). "Notably, on this list, we observed both well-established and candidate oncogenes in Ewing sarcoma, with many of which displayed striking Ewing sarcoma-specific expression profiles (e.g. LINGO1, HOOK1, CITED2 and IGF2BP1)." (PMID 30496486, 2019).
head and neck squamous cell carcinoma (3 papers, 2022 to 2024). A squamous cell carcinoma that arises from any of the following anatomic sites: lip and oral cavity, nasal cavity, paranasal sinuses, pharynx, larynx, and salivary glands. "We further found higher mRNA expression of IGF2BP1 in other SCCs (Head and neck squamous cell carcinoma, HNSCC; Lung squamous cell carcinoma, LUSC; Cervical squamous cell carcinoma, CESC) tissues than in the corresponding normal tissues based on TCGA datasets." (PMID 37644505, 2023).
multiple myeloma (3 papers, 2022 to 2024). "FEZF1-AS1, whose silencing in multiple myeloma leads to increased cell death by regulation of IGF2BP1, an m6A reader." (PMID 39280246, 2024). "FEZF1-AS1 may be silenced in multiple myeloma in order to increase cellular apoptosis by regulation of the m6A reader protein IGF2BP1." (PMID 39280246, 2024).
rectal cancer (3 papers, 2021 to 2025). A primary or metastatic malignant neoplasm that affects the rectum. "The increased expression of IGF2BP1 in chemotherapy non-responder rectal cancer patients was observed using a ROC plotter." (PMID 34203267, 2021). "Nevertheless, we found that IGF2BP1 expression (probe: 227377_at*) was higher in non-responders to any chemotherapy (5-fluorouracil, oxaliplatin, bevacizumab, irinotecan, and capecitabine) than in responder rectal cancer patients." (PMID 34203267, 2021). "Conversely, YBX1 is recognized for its transcriptional control over HR repair genes and ABC transporters in cancer, leading us to posit that YBX1, rather than IGF2BP1, is the critical substrate through which PRMT3 regulates chemoradiotherapy resistance in rectal cancer." (PMID 41147802, 2025).
Sepsis (3 papers, 2022 to 2023). Sepsis is defined as life-threatening organ dysfunction caused by a dysregulated host response to infection. "In conclusion, these findings revealed that m6A methyltransferase METTL3 participated in the myocardial injury induced by sepsis via the IGF2BP1/HDAC4 axis." (PMID 35840562, 2022). "The results indicated that IGF2BP1 played a certain role in sepsis AKI." (PMID 36632449, 2023). "In conclusion, the findings illustrated a role of METTL3/IGF2BP1/m6A/HDAC4 axis on sepsis-induced myocardial injury, which might provide novel therapeutic strategy for septic myocardial injury." (PMID 35840562, 2022). "IGFBP1, IGFBP2, IGF2BP1, and WTAP were highly expressed in advanced sepsis patients, and the remaining 17 regulators were poorly expressed." (PMID 37330481, 2023). "The results showed that IGFBP1, IGFBP2, IGF2BP1, and WTAP were highly expressed in patients with advanced sepsis and m6A cluster B; IGFBP1, IGFBP2, and IGF2BP1 showed a significant positive correlation with Th17 helper T cells." (PMID 37330481, 2023). "IGFBP1, IGFBP2, IGF2BP1, and WTAP were highly expressed in patients with advanced sepsis and m6A cluster B. IGFBP1, IGFBP2, and IGF2BP1 were positively correlated with Th17 helper T cells." (PMID 37330481, 2023). "Based on the RF model and correlation analysis, IGFBP1, IGFBP2, IGF2BP1, WTAP, and METTL16 were screened out to accelerate the occurrence and development of sepsis by regulating m6A methylation and promoting immune cell infiltration." (PMID 37330481, 2023). "IGFBP1, IGFBP2, IGF2BP1, WTAP, and METTL16 may accelerate the development of advanced sepsis by regulating m6A methylation modification and promoting immune cell infiltration." (PMID 37330481, 2023).
thyroid cancer (3 papers, 2021). "In sum, 75% (27/36) of all tested ATC and 0.5% (1/204) of poorly and well-differentiated thyroid carcinoma tissue samples were positive for IGF2BP1 protein." (PMID 32719445, 2021). "This suggests a second layer of miRNA-dependent control settling on RNA-binding proteins such as IGF2BP1, which may promote thyroid carcinoma progression by impairing the miRNA-dependent downregulation of oncogenes." (PMID 34885022, 2021). "Here, we reveal that IGF2BP1 and MAGEA3 are the first reliable protein and RNA markers of ATC, specifically distinguishing this malignancy from any other thyroid cancer of follicular origin, including PDTC." (PMID 32719445, 2021). "Exclusive expression of IGF2BP1 and MAGEA3 in ATC was initially validated by Western blotting in two ATC-derived cell lines (C643 and 8305C) and the individual samples of each thyroid cancer subtype comprised in the test cohort." (PMID 32719445, 2021). "Importantly, we provide confirmatory evidence that IGF2BP1 and MAGEA3 expression distinguishes ATC from poorly differentiated thyroid carcinoma." (PMID 32719445, 2021). "Interestingly, the IGF2 mRNA-binding protein 1 (IGF2BP1) was recently shown to be upregulated in the majority of ATCs, while absent in poorly differentiated and well-differentiated thyroid carcinoma." (PMID 34944959, 2021).